RNU5F-8P (RNA, U5F small nuclear 8, pseudogene)
Gene: Small nuclear RNA gene on chromosome 1 (240,653,367 to 240,653,477, forward strand). Ensembl gene ENSG00000251750.
Homologues: Orthologues: chimpanzee U5 (92% identical), macaque U5 (76% identical). Paralogues in human: RNU5F-7P (81% identical), RNU5F-3P (79% identical), RNU5F-6P (74% identical), RNU5E-7P (68% identical), RNU5E-4P (67% identical), RNU5E-10P (65% identical), RNU5A-7P (64% identical), RNU5E-5P (63% identical), RNU5A-4P (62% identical), RNU5A-3P (61% identical), RNU5A-6P (61% identical), RNU5B-4P (61% identical), and 13 more.